BMP2 (bone morphogenetic protein 2)
Diseases named in the same sentence as BMP2 in open-access papers (continued):
Sharing a sentence is not in itself a finding about the gene and the disease.
hematoma (8 papers, 2020 to 2024). A hematoma is a collection of blood from a vascular structure into an extravascular space. "Future studies are required to understand the optimal dosage and, more importantly, achieve a controlled release of BMP-2 at the defect site to avoid undesired effects such as inflammation, hematoma, and bone cysts." (PMID 38667541, 2024). "In particular, the bFGF loaded in GelMA mimics growth factors from hematoma during the inflammation and soft callus phases of the bone healing process, while BMP-2 bound on MCM mimics growth factors in the hard callus and bone remodelling phases." (PMID 34906152, 2021). "However, several side-effects were reported after the usage of BMP-2, such as hematoma formation, radiculitis, and increased osteolysis, as BMP-2 also enhances osteoclastogenesis." (PMID 39585031, 2024). "In a rat osteotomy model, autologous blood clots loaded with bone morphogenetic protein-2 (BMP2) demonstrated the ability to completely bridge the defect, while in situ hematoma and artificial blood clot groups did not bridge the defect." (PMID 34440188, 2021).
intervertebral disc degeneration (8 papers, 2015 to 2024). "Given the role of FOXO3 in the circFGFBP1 expression, we finally demonstrated that FOXO3-activated circFGFBP1 inhibits ECM degradation and NP cell death via the miR-9-5p/BMP2 axis in intervertebral disc degeneration in vivo and in vitro." (PMID 36986573, 2023). "In patients with intervertebral disc degeneration, miR-129-5p was downregulated along with BMP2 upregulation." (PMID 31999936, 2020). "A series of in vitro and in vivo studies has elucidated the roles of chondrogenesis and the regenerative effect of BMP-2 in the intervertebral disc degeneration process." (PMID 27495942, 2016). "BMP-2 has been shown to accelerate chondrogenesis and extracellular matrix formation, and other studies have indicated that although BMP-2 cannot prevent intervertebral disc degeneration, it can lead to intervertebral disc ossification." (PMID 27495942, 2016).
postmenopausal osteoporosis (8 papers, 2020 to 2025). Metabolic disorder associated with fractures of the femoral neck, vertebrae, and distal forearm. "Collectively, our results suggest that GTE precludes excessive bone loss due to postmenopausal osteoporosis by inducing bone formation through Bmp2-Smads 1/5/8-Runx2 signaling and interrupts osteoclastogenesis via RANKL/OPG binding and lowered Nox-4 activity." (PMID 33096661, 2020). "The BMP/Smad pathway of mesenchymal stem cells (MSCs) was found to be decreased in subjects with postmenopausal osteoporosis, and recombinant human BMP-2 (rhBMP-2) showed positive effects in the OVX-induced mouse model and in a human study of patients with open tibial fractures." (PMID 36902303, 2023). "The present study demonstrated that EECM treatment significantly ameliorates the symptoms of postmenopausal osteoporosis in vivo, by promoting osteoblast differentiation by the induction of BMP2-MAPK-Runx2 signaling, and subsequently by indirect suppression of osteoclastogenesis by OPG." (PMID 32321506, 2020).
tendinopathy (8 papers, 2013 to 2020). "Ectopic expression of BMP-2/4/7 was detected in both clinical samples of tendinopathy and animal tendon injury model." (PMID 33102476, 2020). "Clinical tendinopathy samples have shown that chondro-osteogenic BMPs, including BMP-2, BMP-4, and BMP-7, are expressed." (PMID 27195010, 2016). "The use of pathological concentration of BMP-2 in tendinopathy for TDSC stimulation in vitro would yield more clinically relevant data." (PMID 23964681, 2013). "Ectopic expression of BMP-2, -4 and -7 were observed in clinical samples of tendinopathy and collagenase-induced (CI) tendon injury rat model which showed failed healing and ectopic chondro-ossification in tendons." (PMID 23964681, 2013). "In addition, stronger expression of BMP-2 and weaker expression of BMP-4/7 were observed in and around the chondrocyte-like cells and ossified region in ossified tendinopathy, suggesting the possibility of BMP-2 playing a more vital role in this process." (PMID 33102476, 2020). "Taken together, these studies indicate that the activation of BMP-2 expression in TSPCs during tendon overuse might provide a possible explanation for ectopic calcification in calcifying tendinopathy." (PMID 31737075, 2019). "Involvement of BMP-2 in the pathogenesis of tendinopathy has been suggested previously based on the reported observations that chondrocyte phenotype and ectopic ossification are present in calcifying tendinopathy and based on the expression of BMP-2 protein at those sites." (PMID 31737075, 2019). "Gene and protein expression of TGF-β and protein expression of BMP2, BMP4 and BMP7 were increased in the six studies that compared tendinopathy and healthy tendon tissues from the patella or the Achilles." (PMID 27863509, 2016). "Ectopic expression of BMP-2, BMP-4 and BMP-7 was observed in clinical samples of tendinopathy and collagenase-induced (CI) tendon injury rat model." (PMID 23964681, 2013). "There was ectopic expression of BMP-2, BMP-4 and BMP-7 in clinical samples of tendinopathy and collagenase-induced tendon injury rat model." (PMID 23964681, 2013). "BMP-2, BMP-7 and CTGF mRNA remained unchanged with tendon disease." (PMID 26883016, 2016). "First, the pathological concentration of BMP-2 in tendinopathy was not known." (PMID 23964681, 2013).
ankylosis (7 papers, 2015 to 2024). Fixation and immobility of a joint. "BMP2, which is a growth factor that stimulates chondrocyte differentiation as well as osteoblast differentiation, has been implicated in the process of bone formation and ankylosis in the DBA/1 enthesitis model." (PMID 26801240, 2016). "Exploring experimental SpA models would certainly supply more information on the impact of BMP-2/BMP-4 imbalance in this specific ankylosis." (PMID 33046134, 2020). "A previous study showed that BMP2 is highly expressed at the site of ankylosis in an AS mouse model." (PMID 31024000, 2019). "Nevertheless, as a specific antagonist of BMP2, noggin still has broad application prospects for preventing ankylosis progression in AS." (PMID 31024000, 2019). "However, BMP-2-loaded implants with high concentrations may recruit and activate more bone-resorbing cells than osteoprogenitor ones, eventually inducing opposing effects such as noggins and ankylosis." (PMID 38793339, 2024). "King and Hughes investigated the effects of occlusal loading on ankylosis, bone, and cement formation in the presence and absence of BMP-2 in an in vivo rat fenestration model." (PMID 37298695, 2023). "Additionally, the increase in BMP-2 concentration as a result of the enhancement of cell proliferation may induce normal regeneration without ankylosis, unlike direct administration of BMP-2, which induces ankylosis." (PMID 26120833, 2015).
aortic stenosis (7 papers, 2018 to 2025). Aortic valve stenosis is a aortic valve disease caused by the incomplete opening of the aortic valve. "miR-204 expression is significantly dysregulated in CAVD and aortic stenosis, as are the miR-34 family members that are known to suppress BMP2; making these attractive miR-based therapeutic targets." (PMID 30460247, 2018). "A further step in the development of aortic stenosis is the mineralization of the valve due to the transition of VIC into osteoblast-like VIC characterized by a variety of osteoblastic markers, such as osteopontin, bone morphogenetic protein 2 (BMP2) and Runt-related transcription factor 2 (RUNX2)." (PMID 36982932, 2023).
chronic kidney disease (7 papers, 2018 to 2026). Impairment of the renal function secondary to chronic kidney damage persisting for three or more months. "A study by Dalfino showed that patients with chronic kidney disease presented higher levels of BMP2 compared to healthy controls." (PMID 38535084, 2024). "Mechanistically, they found that ALKBH1 activates bone morphogenetic protein 2(BMP2) and aggravates osteogenic reprogramming in chronic kidney disease." (PMID 38169562, 2024). "Arterial stiffness, common in chronic kidney disease (CKD), may be linked to an imbalance in BMP-2 and BMP-7, leading to renal damage, hypertension, and increased pulse wave velocity (PWV) in CKD." (PMID 39070522, 2024). "This article primarily reviews the molecular mechanisms by which high phosphate, BMP2, and RUNX2 regulate vascular calcification secondary to chronic kidney disease, and discusses the complex interactions among these factors and their impact on the progression of vascular calcification." (PMID 39308809, 2024).
cyst (7 papers, 2015 to 2024). A sac-like closed membranous structure that may be empty or contain fluid or amorphous material. "Phenamil inhibited BMP-2 induced cyst-like bone formation, inflammatory soft tissue swelling and adipogenesis." (PMID 36371202, 2022). "However, treatment with high dose BMP-2 has been reported to have various side effects such as vertebral osteolysis with cyst formation, ectopic bone, cancer and life-threatening inflammatory cervical swelling." (PMID 36371202, 2022). "Next, we will apply high dose BMP2 to induce adverse cyst-like bone formation and inflammation in the mandibular defect model and will test whether phenamil can inhibit BMP2 induced fatty cyst-like structure and inflammatory soft-tissue swelling." (PMID 28790361, 2017). "However, side effects such as heterotopic bone formation, postoperative inflammation, osteolysis and subsidence of implants, and cyst-like bone void formation are of concern and may result from excessive dosing of BMP-2." (PMID 25659106, 2015). "A significantly robust and cyst-like bone formation was observed in the defects treated with scaffolds infused with 1 μg of BMP2 compared to no growth factor." (PMID 38297106, 2024). "A significantly robust and cyst-like bone formation was observed in the defects treated with scaffolds infused with 1μg of BMP2 compared to no growth factor (p<0.05)." (PMID 37841854, 2023). "In contrast, co-treatment with phenamil + BMP2 resulted in dense trabecular structure without cyst formation." (PMID 28790361, 2017). "Moreover, co-treatment with phenamil + BMP2 resulted in dense trabecular structure without cyst formation at all tested BMP2 doses." (PMID 28790361, 2017).
disc degeneration (7 papers, 2009 to 2025). "Although their results indicated a relationship between BMP-2 expression and disc degeneration, the exact relationship remained unclear." (PMID 27495942, 2016). "Third, we studied the role of EA played in the ECM regulatory factors, including MMP-13, TIMP-1, and BMP-2, in disc degeneration." (PMID 24987434, 2014). "Therefore, BMP2 is likely to be another critical end effector mRNA of hsa_circ_7042 and miR-369-3p in regulating disc degeneration." (PMID 36068615, 2022). "We hypothesized that the terminal gene of miR-369-3p that plays a functional role in disc degeneration might also pass through BMP2 in addition to CDH2." (PMID 36068615, 2022). "The degree of disc degeneration may have also resulted in the conflicting observed responses to BMP-2 stimuli." (PMID 19912653, 2009). "When the preliminary information related to disc degeneration in the Genecard database was combined with the target analysis of miR-369-3p, it was found that CDH2 was not included in the database, and the BMP2 gene was the primary target gene obtained by screening." (PMID 36068615, 2022).
endothelial dysfunction (7 papers, 2013 to 2023). In vascular diseases, endothelial dysfunction is a systemic pathological state of the endothelium (the inner lining of blood vessels) and can be broadly defined as an imbalance between vasodilating and vasoconstricting substances produced by (or acting on) the endothelium. "Our findings also suggest that p38/NFκB is implicated in BMP2-induced endothelial dysfunction probably via a VEGF-dependent mechanism." (PMID 33584642, 2020). "Increased levels of BMP-2 exert proinflammatory and proatherogenic effects by inducing oxidative stress and endothelial dysfunction, and have been shown to promote plaque calcification by inducing an osteogenic phenotype in VSMCs." (PMID 27733980, 2016). "The activation of BMP signaling, either by overexpression of BMP2 in vascular cells or administration of recombinant BMPs, results in endothelial dysfunction, oxidative stress and enhanced monocyte adhesiveness to the endothelium." (PMID 24223641, 2013). "Early in the inflammatory process, increased expression of BMP2 could have pro-inflammatory effects by inducing endothelial dysfunction, oxidative stress, and endothelial activation." (PMID 28574846, 2017).
pulmonary arterial hypertension (7 papers, 2020 to 2025). Pulmonary arterial hypertension (PAH) is a group of diseases characterized by mean pulmonary artery pressure >20 mmHg and elevated pulmonary arterial resistance leading to right heart failure. "A genetic mutation in the bone morphogenetic protein 2 (BMPR2) gene has been linked to pulmonary arterial hypertension." (PMID 33663433, 2021). "The interaction with genetic mutations on autosomal genes that cause heritable pulmonary arterial hypertension such as bone morphogenetic protein 2 (BMPR2) are examined." (PMID 34068984, 2021). "For instance, mutations in BMP2 have been associated with primary pulmonary hypertension." (PMID 35048206, 2022). "BMPR1B emerged as a crucial mediator of BMP2 signaling, regulating pulmonary artery smooth muscle proliferation to mitigate high-altitude pulmonary hypertension." (PMID 41153449, 2025). "For example, in hypoxia-induced pulmonary hypertension, BMP2 expression is increased, leading to upregulation of eNOS, as well as induction of endothelial cell survival and motility via Wnt pathways." (PMID 33021694, 2021). "PPARγ, which could be regulated by TRIB3, was reported that inhibited TGF-β signaling and acted as a link between pro-proliferative TGF-β and anti-proliferative bone morphogenetic protein 2 (BMP2) signalings in vascular smooth muscle cells and inhibited pulmonary arterial hypertension." (PMID 33192545, 2020).
radiculitis (7 papers, 2013 to 2025). An inflammatory process affecting a nerve root. "Concerns were addressed regarding complications associated with the use of BMP-2 in spinal indications, which include radiculitis, osteolysis, retrograde ejaculation, and ectopic bone formation." (PMID 23957727, 2013). "Given the previous concerns about BMP-2, such as inflammation, radiculitis, seroma, ectopic bone growth, and probable carcinogenicity, this finding is of the utmost importance." (PMID 38541958, 2024). "While BMP-2 shows desired outcomes in regenerating bone defects, higher risks in radiculitis, ectopic bone formation, osteolysis, and inferior global products are reported by a peer-review on 13 industry-sponsored BMP-2 projects." (PMID 34831216, 2021). "Although BMP-2 promotes fracture healing, several post-surgical complications arose, including ectopic bone formation, radiculitis, vertebral osteolysis, increased microfracture occurrence, low bone healing efficacy, and hematoma formation." (PMID 32933207, 2020). "However, clinical use is limited due to high cost, restricted availability, and adverse events, such as ectopic ossification, radiculitis, and excessive swelling, particularly with recombinant human BMP-2." (PMID 41458709, 2025).
anemia (6 papers, 2014 to 2024). A reduction in the number of red blood cells, the amount of hemoglobin, and/or the volume of packed red blood cells. "Investigating variant rs235756 in the BMP2 gene, which has previously been associated with hepcidin-induced anemia and iron overload, is essential for an encompassing understanding of iron metabolism disorders." (PMID 39599580, 2024). "Hepcidin excesses inducing anemia and hepcidin deficiencies inducing iron overloads have been associated with BMP2." (PMID 34780475, 2021). "Genotypes and allele frequencies of BMP2 (rs235756) polymorphism in normal subjects and in iron deficiency anemia group." (PMID 34780475, 2021). "Secondly, the BMP2 was associated with ferritin in the previous GWAS for elderly Chinese women with iron-deficiency anemia." (PMID 25162662, 2014). "The secreted levels of BMP2 and FKN were also determined after the development of anemia." (PMID 37175630, 2023). "FKN induces the secretion of the receptivity-related cytokines at anemia, which may improve endometrium receptivity via the CX3CR1 and the regulation of the NFκB pathway and by regulating activin, follistatin, and BMP2, as well as PR, SOX-17, PTGER2, and TIMP2." (PMID 37175630, 2023).
embryonic carcinoma (6 papers, 2004 to 2016). "In embryonic carcinoma cells treated with BMP-2 to adopt an epithelial phenotype, miR-518b was shown to directly target FOXN1—a transcription factor critical for thymus development and epithelial differentiation." (PMID 27529341, 2016). "Specifically, BMP-2 can induce its own expression in human embryonic carcinoma cells." (PMID 20567515, 2010). "Our results, obtained in an anamniotic model system, the Xenopus embryo, and in murine embryonic carcinoma cells, indicate that MAB21L2 interacts functionally with SMAD1, a nuclear transducer of BMP2/4/7 signaling." (PMID 15613244, 2004). "The NT2 cell line, which is a human embryonic carcinoma cell line, differentiates into post-mitotic neuron-like cells following treatment with all trans retinoic acid (ATRA) and into non-neural epithelial cell lineages following exposure to bone morphogenetic protein 2 (BMP-2)." (PMID 22128244, 2011).
periodontal disease (6 papers, 2017 to 2025). "BMP-2 plays an important role in treating bony defects caused by surgical resection or periodontal disease." (PMID 35958094, 2022). "Key examples include mRNA encoding BMP-2 for tissue regeneration, mRNA vaccines for HPV-related cancers, antisense oligonucleotides for bacterial virulence in dental caries, and immunomodulation for periodontal disease." (PMID 39996953, 2025). "In particular, ASU has shown efficacy against periodontal disease by modulating the expression of transforming growth factor beta 1 (TGF-β1), TGF-β2, and bone morphogenetic protein 2 (BMP-2)." (PMID 31554332, 2019). "Consequently, we developed a scaffold laden with mBMSCs, BMP2, and PDGF via 3D bioprinting to address the repair of the defects resulting from periodontal disease." (PMID 37509098, 2023).
renal fibrosis (6 papers, 2012 to 2022). A final common manifestation of a wide variety of chronic kidney diseases characterized by glomerulosclerosis and tubulointerstitial fibrosis. "BMP-2 is previously reported to be effective in preventing renal fibrosis, the underlying mechanism is linked with the reduction of TGF-β RI and down-regulation of Smads signalling." (PMID 22283839, 2012). "In experimental models of chronic pancreatitis, renal fibrosis, and pulmonary fibrosis, BMP2 has been reported to have anti-fibrotic properties, mainly related to inhibition of TGF-β-related pathways." (PMID 33561140, 2021). "BMP2 antagonizes renal fibrosis in the rat ureter obstruction model in vivo and promotes the catabolism of the type I TGFβ receptor in renal fibroblasts." (PMID 25849157, 2015). "The role of BMP2 in renal fibrosis seems to be controversial." (PMID 35784691, 2022). "Our results indicated that the YSHS granule may be an effective drug to alleviate glomerular fibrosis in FSGS and BMP2 may be served as an effective therapeutic target in the treatment of renal fibrosis and FSGS." (PMID 35784691, 2022). "BMP-2, -4, and -7 have been demonstrated to have anti-inflammatory activity in the stomach of mice, and BMP-6 and -7 are protective in renal fibrosis." (PMID 29849494, 2018).